EPO (erythropoietin)
Diseases named in the same sentence as EPO in open-access papers (continued):
Sharing a sentence is not in itself a finding about the gene and the disease.
renal fibrosis (continued). "Previous studies reported that EPO functions as an EMT inhibitor in the kidneys and was effective in ameliorating renal fibrosis." (PMID 32154256, 2020). "Pathway enrichment analysis showed that the candidate targets were mostly related to the TGF-β, the p38MAPK, and the erythropoietin (EPO) receptor signaling pathways, which are known contributors to renal fibrosis and/or renal anemia." (PMID 28915563, 2017). "Meanwhile, some other mediators are found to exert marked anti-fibrotic effects in the pathogenesis of renal fibrosis, such as HGF (hepatocyte growth factor), EPO (erythropoietin) and BMP-7 (bone morphogenetic protein-7)." (PMID 24844766, 2014). "EPO-producing ability is decreased in REP and contributes to renal fibrosis." (PMID 34576149, 2021). "Moreover, EPO administration in an animal model of CKD was found to suppress EMT and inflammatory cell infiltration, thus reducing renal fibrosis." (PMID 32993806, 2020). "Another study of transgenic mice found that enhanced signaling mediated by hypoxia-inducible factor (HIF) in myofibroblast-transformed renal EPO-producing cells reactivated the synthesis of EPO, without influencing renal fibrosis or inflammation." (PMID 32154256, 2020). "Our finding could be supported by the recent report that selective disruption of TGF-βR2 in renal PDGFRβ+ cells preserves EPO production but no discernible effect on myofibroblast markers in the murine model of renal fibrosis." (PMID 34724959, 2021). "However, under pathologic conditions the resident renal fibroblasts transdifferentiate into myofibroblasts, which promote renal fibrosis by producing large amounts of extracellular matrix proteins rather than EPO." (PMID 32154256, 2020). "EPO treatment has also been found to reduce renal fibrosis in a murine model of unilateral ureteral obstruction (UUO) by inhibiting TGF-β1-induced EMT, suggesting that inhibition of EMT by EPO administration could be a potential therapeutic strategy to inhibit or slow CKD progression." (PMID 32993806, 2020). "Moreover, EPO has been shown to upregulate miR-200 expression and attenuate hypoxia-induced EMT in HK-2 cells as well as counteract TGF-β1-induced EMT by regulating TGF-β/Smad-2 signaling and inhibit renal fibrosis in UUO kidneys." (PMID 32993806, 2020). "Interestingly, fibroblasts from damaged tubular epithelial cells have no significant contribution in renal fibrosis, but renal erythropoietin-producing cells, originating from neural crests, differentiate into myofibroblasts in long time exposure to inflammation." (PMID 25340134, 2013).
diabetic retinopathy (34 papers, 2007 to 2025). "Previous studies have reported variable findings regarding the relationship between this EPO polymorphism and diabetic retinopathy." (PMID 39940677, 2025). "In sum, the data demonstrate a significant differential distribution of EPO polymorphism genotypes and alleles between the control and diabetic retinopathy groups." (PMID 41196916, 2025). "Genotype and allele frequencies for EPO polymorphism (rs1617640C>T/G) across the samples and their association with diabetic retinopathy during present study." (PMID 41196916, 2025). "In conclusion, this study provides compelling evidence that the EPO gene polymorphism (rs1617640 C > T/G) is significantly associated with the risk of diabetic retinopathy in Punjabi patients with T2DM." (PMID 41196916, 2025). "Clinical studies show evidence of a beneficial association between increased endogenous EPO and reduced diabetic retinopathy in humans." (PMID 32785675, 2020). "Diabetic kidney dysfunction decreases the secretion of erythropoietin that causes chronic anemia and retinal tissue and cellular hypoxia, and kidney dysfunction is known to be a risk factor for developing diabetic retinopathy and DME." (PMID 31885887, 2019). "A particular polymorphism of the erythropoietin promoter associated with increased erythropoietin production is associated with severe diabetic retinopathy and renal disease." (PMID 29429414, 2018). "Gong associated higher diabetic retinopathy risk with carrying the TT/GT genotype and T allele at the EPO gene site rs1617640." (PMID 29348855, 2017). "Only one study investigated the relationship between EPO rs507392 polymorphisms and diabetic retinopathy." (PMID 29348855, 2017). "We investigated the association of signals from previous GWAS and candidate gene meta-analyses for diabetic retinopathy (DR) or nephropathy (DN), as well as an EPO variant in meta-analyses of severe (SDR) and mild diabetic retinopathy (MDR)." (PMID 25487307, 2015). "The analysis of genotype and allele frequencies for the EPO polymorphism (rs1617640 C > T/G) between the CDR and DR groups reveals significant associations with the occurrence of diabetic retinopathy." (PMID 41196916, 2025). "EPO is being studied in other models of ocular diseases, such as diabetic retinopathy, retinal vein occlusion, optic neuritis, and ischemic optic neuropathy, also aiming at retinal and optic nerve protection and regeneration." (PMID 37259314, 2023). "Studies on diabetic retinopathy found that EPO is released in response to tissue damage and appears to have protective functions." (PMID 36077032, 2022). "Abundant data show the high relevance of this paracrine/autocrine system of tissue protection and repair for diabetic retinopathy (DR), with impressive efficacy of EPO, as well as engineered mimetics, in preclinical models." (PMID 32674280, 2020). "Neuroprotective effects in the retina in experimental diabetic retinopathy models have also been observed with EPO." (PMID 32674280, 2020). "Erythropoietin (EPO) is one of the systemic angiogenic factors, and its role in ocular angiogenesis and in diabetic retinopathy (DR) is not yet fully understood." (PMID 31727007, 2019). "It is considered that erythropoietin can have direct role in pathophysiology of diabetic retinopathy." (PMID 31727007, 2019). "In our study a significantly higher concentration of erythropoietin in serum in severe forms of diabetic retinopathy was determined." (PMID 31727007, 2019). "Reports on safety in ganglion cell protection invited experimental and human trials of using EPO in glaucomas, diabetic retinopathies, optic neuritis, and neuropathies." (PMID 30647957, 2018). "EPO is neuroprotective, which has been shown in various animal studies e.g. in diabetic retinopathy." (PMID 25013951, 2014). "Many other authors described positive effects of EPO on the pathomechanism of diabetic retinopathy, e.g. reduced gliosis, increased RPE barrier function or less pericyte loss." (PMID 25013951, 2014).
diabetic retinopathy (continued). "Positive effects of external EPO on neuronal survival and function have been shown in other animal models, e.g. in diabetic retinopathy or autoimmune neuropathy." (PMID 25013951, 2014). "All patients completing this trial are eligible to enter a 2-year follow-up study to enable monitoring of emergent adverse events, anti-erythropoietin antibody responses, maintenance of efficacy and changes in diabetic retinopathy status." (PMID 17999759, 2007). "EPO improved oxygen carriage to retinal tissue and ameliorated diabetic retinopathy." (PMID 34621759, 2021). "Therefore, EPO can be considered a therapeutic tool for the treatment of diabetic macular oedema during diabetic retinopathy." (PMID 34299300, 2021). "The model treats only one cytokine, a single VEGF isoform without consideration of other larger VEGF isoforms, PEDF, PDGF, erythropoietin, angiopoetin-1, angiopoetin-2 or angiopoetin-like 4, all of which likely play at least some role in vascular changes in diabetic retinopathy." (PMID 27300722, 2016). "Erythropoietin (EPO) has been linked to both ROP and diabetic retinopathy." (PMID 22355249, 2012). "Careful inhibition of EPO may prove to be an effective way to treat or prevent diabetic retinopathy and other forms of angiogenesis." (PMID 19930719, 2009). "Future studies with additional samples may lead to more conclusive answers regarding the potential role of EPO in diabetic retinopathy." (PMID 19930719, 2009). "Furthermore, experimental studies have reported that EPO could protect the inner blood–retinal barrier, the outer blood–retinal barrier and neuronal cells in early diabetic retinopathy." (PMID 36077032, 2022). "We can conclude that erythropoietin represents one of the most important growth factors that, together with other angiogenic factors, like vascular endothelial factor, participates in ischemic and angiogenic processes in diabetic retinopathy, especially at its proliferative stage." (PMID 31727007, 2019). "However, several important effects of EPO in the body are independent of its hematopoietic activity, and this is how EPO causes diabetic retinopathy changes." (PMID 31727007, 2019). "EPO may play a direct role in the pathophysiology of diabetic retinopathy." (PMID 19930719, 2009). "During diabetic retinopathy, inner blood-retinal barrier (BRB) breakdown occurs while EPO prevents this damage via the inhibition of microglial activation and phagocytosis mediated by the SRC/AKT/COFFILIN signaling pathway." (PMID 34299300, 2021). "EPO was demonstrated to protect against the VEGF-induced permeability of the blood-brain barrier (BBB) through restoring the tight junction proteins and VE-cadherin in experimental diabetic retinopathy and in vitro bovine model." (PMID 34621759, 2021). "EPO mitogenic and antiapoptotic effects on the endothelium prevent ischemic retinal cell death in early diabetic retinopathy and chronic nonresistant macular edema." (PMID 30647957, 2018). "In a post-mortem analysis, retinas from diabetic patients without diabetic retinopathy had higher EPO mRNA levels than age-matched controls." (PMID 23878504, 2013). "EPO was found to be more strongly associated with diabetic retinopathy than VEGF, and the level of EPO in the vitreous did not correlate with plasma level, suggesting local production of EPO." (PMID 22567318, 2012). "Some processes relevant to diabetic retinopathy were found upregulated in diabetic aqueous samples including CD40, C reactive protein, erythropoietin, fatty acid binding protein, FGF basic, fibrinogen, IL-1ra, IL-8, leptin, macrophage-derived chemokine (MDC), MMP-2, and VEGF." (PMID 19145248, 2009). "Recent evidence suggests erythropoietin (EPO) and the erythropoietin receptor (EPOR) may play a direct role in the pathogenesis of diabetic retinopathy." (PMID 19930719, 2009).
diabetic retinopathy (continued). "Furthermore, accumulating findings have also outlined the promising use of EPO in the treatment of retinal degenerative diseases, such as AMD, retinitis pigmentosa, and diabetic retinopathy." (PMID 30108483, 2018).
Thrombocytopenia (34 papers, 2007 to 2025). A reduction in the number of circulating thrombocytes. "The dual role of iron in the creation of platelets, which is necessary for the production of an integral section of the platelet, and the diphasic response of platelets to erythropoietin are the hypothesized causes of thrombocytopenia in patients with IDA." (PMID 38655566, 2024). "For example,if patients exposed to chemotherapy have grade 3 or 4 thrombocytopenia,then EPO-RA administration should be reduced or delayed to avoid moresevere thrombocytopenia." (PMID 38093847, 2023). "Of these, 5 events (acute respiratory distress syndrome, pneumonia, pulmonary embolism, neutropenia and thrombocytopenia) were considered to be related to EPO." (PMID 21959870, 2011). "There were elevations of serum erythropoietin and transaminase and hypoalbuminemia, hypofibrinogenemia, thrombocytopenia, elevated prothrombin time and partial thromboplastin time, and disseminated fibrin deposition and hemorrhage." (PMID 17520025, 2007). "In conclusion, our meta-analysis showed that EPO treatment would not increase the risk of adverse events (thrombocytopenia, hypotension, and hepatic and kidney injury)." (PMID 36699298, 2022). "The comparison of possible adverse events of EPO: EPO treatment would not increase the risk of thrombocytopenia, hypotension, and hepatic and kidney injury." (PMID 36699298, 2022). "We describe the case of a JW female presenting with new-onset, acutely worsening AIHA and thrombocytopenia with concern for hemodynamic compromise who was successfully treated with erythropoietin-stimulating agents, parenteral iron, folic acid, and high-dose steroids." (PMID 34277157, 2021). "This reduction in endogenous erythropoietin might decrease the productivity of megakaryocytes and lead to transient thrombocytopenia." (PMID 33042656, 2020). "Previous reports demonstrated an association between reduced ITPase activity and treatment-induced thrombocytopenia, likely in relation to the decline in Hb, or due to the increased stimulation of megakaryocyte-erythroid progenitor cells by erythropoietin production." (PMID 29851985, 2018). "Additionally, chronic exposure to increased levels of erythropoietin in the fetus due to fetal hypoxia secondary to preeclampsia may also lead to thrombocytopenia by suppressing the megakaryocytic cell line which may lead to decreased platelet production." (PMID 40221464, 2025). "The mechanism behind thrombocytopenia is unclear, but it may be due to an alteration in the activity of iron-dependent enzymes in thrombopoiesis or early response to direct stimulation of the erythropoietin (EPO) receptor on megakaryocytes or shunting into the erythroid precursors' pathway." (PMID 37829950, 2023).
type 2 diabetes (34 papers, 2012 to 2025). "Furthermore, additional analysis of the TREAT trial of patients with kidney disease and type 2 diabetes suggested that a poor initial response to EPO was associated with a lower hemoglobin level at 12 weeks, higher EPO dose and increased risk of cardiovascular events or death." (PMID 24918289, 2014). "In patients with type 2 diabetes, serum erythropoietin levels are low even with normal renal function, and as glycated hemoglobin levels increase, erythropoietin is further reduced." (PMID 38304078, 2024). "Here, we assessed the short-term effect of fresh PJ on the level of EPO in patients with type 2 diabetes (T2D) compared to healthy individuals." (PMID 31139640, 2019). "Previously, we have shown that in a group of patients with type 2 diabetic CKD, elevated EPO levels were strongly associated with classical markers of inflammation and were also independently predictive for mortality." (PMID 25894587, 2015). "This study is aimed at investigating the potential mechanisms by which EPO improves glucose tolerance in an animal model of type 2 diabetes." (PMID 23326455, 2013). "Our study demonstrates for the first time that PPARγ is essential for EPO-induced improvements in hepatic insulin resistance, which supports the idea that EPO may contribute to a novel strategy for treating insulin resistance and type 2 diabetes." (PMID 26643367, 2015). "Here, we assessed the short-term effect of fresh PJ on the level of Erythropoietin (EPO) in patients with type 2 diabetes (T2D) compared to healthy individuals." (PMID 31139640, 2019). "In summary, these findings suggest that PPARγ is involved in EPO/EPOR-induced AKT activation, and targeting the PPARγ/AKT pathway via EPO may have therapeutic implications for hepatic insulin resistance and type 2 diabetes." (PMID 26643367, 2015). "One clinical study has demonstrated that a non-erythropoietic peptide engineered from EPO could have beneficial effects on metabolic parameters and neuropathic symptoms in adults with Type 2 diabetes." (PMID 28288167, 2017).
Alzheimer disease (33 papers, 2009 to 2026). A progressive, neurodegenerative disease characterized by loss of function and death of nerve cells in several areas of the brain leading to loss of cognitive function such as memory and language. "Erythropoietin treatment also increased the hippocampal response during picture encoding and retrieval in human and increased expression of the EpoR has been found in postmortem analyses of patients with Alzheimers disease." (PMID 23497299, 2013). "During chronic neurodegenerative disorders such as cognitive loss and Alzheimer’s disease, EPO may prevent cell toxicity, reduce β-amyloid burden, and lead to improvements in memory." (PMID 23109841, 2012). "In addition, the potential protective capacity of EPO and Wnt1 during Alzheimer’s disease may be linked to the ability of EPO and Wnt1 to govern Bad, Bcl-xL, and caspase activity and increase microglial cell survival during Aβ toxicity." (PMID 23109841, 2012). "Erythropoietin (EPO) is a potential therapeutic for Alzheimer’s disease (AD), but has limited brain penetration, requiring high systemic doses that lead to hematopoietic side effects." (PMID 40585228, 2025). "In a murine model of Alzheimer's disease (AD), intraperitoneal administration of recombinant human erythropoietin (EPO) resulted in significant improvements in memory function relative to saline-treated controls." (PMID 39744428, 2025). "Hypoxia induced hippocampal neurogenesis in adult rats modeling depression and elicited the cerebrocortical expression of erythropoietin and brain-derived neurotrophic factor in transgenic mice modeling Alzheimer’s disease." (PMID 41301754, 2025). "For example, in a rat model of Alzheimer’s disease, systemic injection of EPO enhanced neuronal proliferation in the dentate gyrus." (PMID 38084331, 2023). "For example, systemic administration of EPO has been found to reduce neural tissue damage in mouse models of ischemia, traumatic brain injury, autoimmune encephalitis, seizures, Alzheimer’s disease, and amyotrophic lateral sclerosis." (PMID 38084331, 2023). "The LTP-enhancing effect of EPO is particularly pertinent in diseases with prominent cognitive dysfunction such as Alzheimer’s disease (AD), where it rescues impaired LTP and memory deficits." (PMID 34552490, 2021). "The results from several studies indicate that erythropoietic EPO is therapeutic for a broad range of neurodegenerative diseases such as axonal degeneration, peripheral nerve injury, experimental brain injury, and Alzheimer’s disease." (PMID 34070383, 2021). "The effectiveness of erythropoietin (EPO) combined with SLN in the prevention of Alzheimer’s disease was evaluated." (PMID 33801619, 2021). "EPO also decreased activated microglia expression in autoimmune encephalomyelitis, Alzheimer disease, and ischemic brain injury." (PMID 29201540, 2017). "EPO treatment can be useful in different diseases of the neuroglialvascular unit, e.g. Alzheimer's disease, furthermore treatment with EPO-like peptide, missing the side effects of EPO but still providing its protective function, is possible." (PMID 25013951, 2014). "Comparison of APP/PS1 and age-matched WT control mice revealed a stronger expression of EPOR but a weaker one of EPO in the Alzheimer’s disease (AD) model mice." (PMID 24124607, 2013). "In cell models of Alzheimer’s disease, Aβ degeneration of microglia is limited by EPO through combined activation of PI 3-K and mTOR pathways." (PMID 23109841, 2012). "However, consistent with our findings, EPO levels in the cerebrospinal fluid (CSF) of patients with ALS have been reported to be reduced compared to those in patients with Alzheimer’s disease and individuals with tension-type headache serving as controls." (PMID 41602576, 2026).